RNU6-1178P (RNA, U6 small nuclear 1178, pseudogene)
Gene: Small nuclear RNA gene on chromosome 17 (20,894,532 to 20,894,638, reverse strand). Ensembl gene ENSG00000252483.
Homologues: Orthologues: chimpanzee U6 (94% identical), macaque U6 (85% identical), mouse Gm22997 (75% identical), pig U6 (73% identical), pig U6 (71% identical), rat U6 (69% identical). Paralogues in human: RNU6-467P (94% identical), RNU6-405P (93% identical), RNU6-819P (82% identical), RNU6-490P (81% identical), RNU6-127P (80% identical), RNU6-333P (80% identical), RNU6-480P (80% identical), RNU6-774P (80% identical), RNU6-1239P (79% identical), RNU6-1268P (79% identical), RNU6-1318P (79% identical), RNU6-38P (79% identical), and 1286 more.